TNF (tumor necrosis factor)
Diseases named in the same sentence as TNF in open-access papers (continued):
Sharing a sentence is not in itself a finding about the gene and the disease.
tumor (continued). "Meanwhile, MSL was demonstrated to significantly ameliorate the tumor inflammatory microenvironment by inhibiting pro-inflammatory factors (e.g., TNF-α, IL-6)." (PMID 40528838, 2025). "These cells mediate tumor suppression through mechanisms such as antigen presentation, secretion of pro-inflammatory cytokines (e.g., interferon-γ, TNFα), production of ROS, and direct cytotoxic killing of malignant cells." (PMID 40422235, 2025). "NO also affects the immune environment of the tumor: it promotes the secretion of cytokines (TNF-α, IL-6, IL-8), reprograms macrophages to an M2 phenotype, and promotes T-reg expansion, leading to tumor immunotolerance." (PMID 40649317, 2025). "The pro-inflammatory cytokines TNFα and IFNγ can improve tumor responsiveness to immune checkpoint inhibitors by enhancing T-cell infiltration and activation within the tumor." (PMID 41008842, 2025). "M1 macrophages are pro-inflammatory and can enhance anti-tumor immune responses by secreting cytokines (such as TNF-α and IL-12)." (PMID 40557321, 2025). "Nonetheless, the role of tumor necrosis factor (TNF) produced by CAFs is complex; while TNF can activate fibroblasts, its tumor-promoting, immunosuppressive effects are tied to the suppression of TNF signaling." (PMID 40313969, 2025). "For example, compared with wild-type mice, ACSL4-knockout mice exhibited reduced CD8+ T cell infiltration in tumors, decreased IFN-γ and TNF-α expression, lower tumor cell lipid peroxide levels, and accelerated tumor growth." (PMID 41035634, 2025). "Our findings suggest that Lan C exerts its effects by modulating the TNF/IL-17 signaling pathway, influencing the tumor microenvironment and regulating key processes involved in tumor progression, immune response, and apoptosis." (PMID 40141200, 2025). "Inactivation of GLUT1 enhances the sensitivity of tumor cells to TNF-α-induced anti-tumor immunity by elevating ROS levels." (PMID 39897050, 2025). "Second, blood loss promotes systemic release of pro-inflammatory cytokines including IL-6 and TNF-α, establishing a chronic inflammatory environment conducive to tumor proliferation and metastasis." (PMID 41019554, 2025). "They emphasize TNF’s role in fostering an immunosuppressive, pro-tumor microenvironment and directly conferring therapy resistance by activating NF-κB and anti-apoptotic pathways." (PMID 41007766, 2025). "The Akt/p38 pathway is activated by TANs, which turn MSCs into TAFs and promote tumor cell proliferation and metastasis via the production of cytokines, such as IL-17, IL-23, and TNF-α." (PMID 40422244, 2025). "The major subset, Vγ9Vδ2 T cells, exhibits potent anti-tumor activity when activated, directly lysing tumor cells and secreting pro-inflammatory cytokines such as interferon gamma (IFNγ) and tumor necrosis factor alpha (TNFα)." (PMID 40075663, 2025). "Single-cell RNA sequencing (scRNA-seq) of circulating tumor cells (CTCs) treated with OC should map shifts in the TNF-α–NF-κB–IL-8 axis, elucidating OC’s capacity to mitigate pro-metastatic signaling trajectories." (PMID 40564985, 2025). "For instance, activation of TLR4 can promote the secretion of pro‐inflammatory cytokines and chemokines, such as IL‐6, IL‐10, and TNF‐α, which can create an immunosuppressive microenvironment that facilitates tumour growth and metastasis." (PMID 40696496, 2025). "THRs further impact the tumor microenvironment by regulating cytokines such as TNF-α and IL-6, contributing to immune evasion and cancer progression." (PMID 40926269, 2025). "Radiotherapy also enhances adaptive immunity through interferon γ (IFN-γ), tumor necrosis factor α (TNF-α), and activation of tumor-specific T cells." (PMID 40835598, 2025). "TNF-α serves as a soluble toxic medium produced by liver Kuff cells (KC), mediating the inflammation, tumor cell proliferation and apoptosis." (PMID 41333471, 2025).
tumor (continued). "Immunohistochemistry (IHC) confirmed elevated expression of the cytotoxic effector cytokines (GzmB, IFN-γ, TNF-α) in tumor tissues of uPA–/– mice, whereas ELISA confirmed increased serum levels of these cytokines in uPA–/– tumor-bearing mice." (PMID 40959092, 2025). "Intracellular cytokine analysis revealed that ITM were skewed toward IL-10 production, while NCM predominantly produced TNF and IL-12, suggesting a potential anti-tumor role for the latter subset." (PMID 41219641, 2025). "T cells and monocytes secrete large amounts of pro-inflammatory cytokines, such as IL-2, IL-6, and TNFα, when co-cultured with TCam-2 cells, an effect which is significantly reduced when immune and tumor cells are separated by a Transwell insert." (PMID 40649953, 2025). "Meanwhile, TNFRSF18− T cells have exhibited stronger immunoregulatory activity through the TNF pathway, while tumour cells with high stemness characteristics (high expression of RPS7/RPL30/RPL8) were more resistant to TNF‐mediated immunoregulation." (PMID 40770837, 2025). "In head and neck cancer models, targeting SPP1+ macrophage derived cytokines, particularly TNF-α and IL-1β with the inhibitor significantly impaired tumor cell proliferation and migration in vitro and reduced tumor growth in vivo." (PMID 41425545, 2025). "Cancer-associated adipocytes secrete the chemokines CCL2/5 and IL-6/TNF-α, which promote tumour proliferation and immune escape by binding to CXCR2 and IL-6R/TNF-R on the surface of tumour cells." (PMID 40414892, 2025). "The serum VEGF levels decreased at the highest dosage of PPE compared to the control, leading to tumor growth inhibition and increased TNF‐α levels in serum." (PMID 40200651, 2025). "M1 macrophage-derived exosomes enhance local inflammation and promote the conversion of M0 macrophages into pro-inflammatory, anti-tumor phenotypes by releasing cytokines such as IL-6, IL-12, and TNF-α." (PMID 40573922, 2025). "Preclinical studies underscore the importance of TNF–NF-κB signaling in both tumor initiation and progression, as well as in maintenance of mucosal homeostasis." (PMID 40558596, 2025). "Exogenous expression of B7-H4 in 4T1 resulted in fewer IFN-γ+ and TNF-α+CD8+ T cells in the tumor microenvironment as compared to controls." (PMID 40341398, 2025). "It intimates a potential role for TNF secreted by Macro_CCL4 in modulating T cell activation and enhancing the cytotoxic capacity against tumor cells." (PMID 40520886, 2025). "This is partly due to reduced food intake and the effects of tumour factors and inflammatory cytokines like TNFα that inhibit lipogenesis or promote lipolysis." (PMID 40362192, 2025). "QNZ (EVP4593) targets TNFα production, suggesting that systemic TNFα production plays a role in inhibiting tumour progression in the presence of trametinib." (PMID 41188521, 2025). "The elevated ILF3 expression in CRC appears to be partly due to stimulation by tumor necrosis factor alpha (TNF-α) from the tumor inflammatory microenvironment." (PMID 40695795, 2025). "Visaria et al46 developed a new nanoparticle delivery system including 33-nm polyethylene glycol-coated (PT-cAu-TNF-A) GNPs with the incorporated cytokine TNF-α to enhance tumor damage." (PMID 40242201, 2025). "It has been well established that in the TME, neutrophils and macrophages produce reactive oxygen species (ROS) and nitric oxide (NO), which are cytotoxic for tumor cells, and secrete anti‐tumor cytokines such as tumor necrosis factor (TNF)‐α." (PMID 40257446, 2025). "TNF also attracts endothelial cells, fibroblasts, and pericytes to the tumor site, facilitating the formation of a supportive tumor microenvironment that is conducive to further growth and spread." (PMID 40821768, 2025).
tumor (continued). "For instance, Fusobacterium nucleatum has been shown to modulate the tumor microenvironment by inducing the expression of pro-inflammatory cytokines such as IL-6, IL-17, and tumor necrosis factor α, which promote angiogenesis and tumor cell metastasis." (PMID 40110192, 2025). "Targeted BIRC2 knockdown, when combined with anti‐PD‐1 therapy, significantly suppressed tumour growth, enhanced CD8+ T cell infiltration, and amplified IFN‐γ and TNF‐α secretion in tumour models." (PMID 40159652, 2025). "This shift in cell surface marker expression suggests that TNF EVs actively promote a transition toward a tumor stem cell-like state, highlighting their role as key modulators of the tumor microenvironment." (PMID 40567500, 2025). "IL-6 and TNF can affect all stages of tumor growth, such as initiation, promotion, progression, and metastasis." (PMID 39802656, 2025). "Salmonella typhimurium VNP20009 requires slyA, STM3120, and htrA genes for tumor colonization and immune activation via TNF-α/IL-1β induction, though its clinical translation has been limited by attenuated tumor colonization in humans." (PMID 40297102, 2025). "NF-kB activation upregulates cytokines and growth factors in gene expression, promoting proliferation, tumor cell survival, and angiogenesis (through IL-6, IL-8, TNF-α, and COX-2 upregulation)." (PMID 40723879, 2025). "The antigen specificity and cytolytic function of C.M7R T cells was similar to that of C.M T cells, as was the secretion of effector cytokines IFN-γ and TNF-α upon exposure to the tumor cells." (PMID 40808942, 2025). "N1 neutrophils are key players in anti-tumor immunity, stimulating immune responses through the secretion of TNF-α, IL-12 and IFN-γ, exerting direct cytotoxicity via protease release, and limiting tumor progression by inhibiting angiogenesis." (PMID 40211394, 2025). "This is supported by evidence from anti-TNF therapies in other malignancies, which have shown promising results in reducing tumor progression." (PMID 40299527, 2025). "In the process of skin damage repair, the trend of expression and significance of TNF‐α and TGF‐β has important biological and clinical significance." (PMID 40536887, 2025). "Cancer, especially advanced cancer, further amplifies this inflammatory milieu: tumours secrete cytokines (such as IL-1β, IL-6, and TNF-α) as part of immune evasion and tumour progression processes." (PMID 41149069, 2025). "This is highlighted by increased presence of cytokines like interferons (IFNs) and tumor necrosis factor alpha (TNF-α), produced by tumor cells and responding immune cells, which support the activity of immune cells and impair tumor growth." (PMID 41322194, 2025). "Although TNF-α is classically pro-inflammatory, it can also support tumor cell survival and chronic inflammation, further promoting cancer progression." (PMID 40868199, 2025). "In co-culture assays, it enhanced T cell-dependent tumor killing and restored the expression of key cytokines (GZMB, IFN-γ, IL-2, TNF-α) suppressed by tumor-derived immunosuppression." (PMID 41373467, 2025). "We also found an upregulation of CCL2 (P < 0.01), suggesting macrophage infiltration and accentuated tumor endothelial-mesenchymal transition as well as increased mRNA expression of TNF (P < 0.01)." (PMID 39305371, 2025). "The activation of the TNF-NFKB axis has already been revealed in several tumor types including GBM, while here, through a systematic analysis, we unraveled its association with spatial intratumoral heterogeneity, with consistency in several patient samples." (PMID 40781324, 2025). "Further research is required to delineate the specific alterations within the TNF signaling pathway that enhance tumor sensitivity to T cell-mediated killing, as well as the precise mechanisms involved." (PMID 41315176, 2025).
tumor (continued). "M1-like macrophages can eliminate pathogens and tumor cells by secreting pro-inflammatory cytokines, including interleukin (IL)-12p40 and tumor necrosis factor-alpha (TNF-α)." (PMID 40426926, 2025). "For patients responding to ICB therapy, T cell-derived TNF is particularly crucial for mediating cytotoxicity, and increasing tumor sensitivity to TNF can potentially overcome tumor resistance." (PMID 41315176, 2025). "Growth factors such as EGF, VEGF, FGF, IL‐10, IL‐6, TNF‐α, IFNγ produced by TAMs and NKs and miRNAs carried in tumour‐derived EVs promote tumour proliferation by activating pathways such as RAS–RAF–MEK–ERK–MAPK and PI3K–AKT–mTOR." (PMID 40525649, 2025). "It is known that CD8+ T cells secrete cytokines interferon-γ (IFN-γ) and tumor necrosis factor-α (TNF-α) to kill tumor cells." (PMID 40380202, 2025). "Laboratory findings have highlighted that targeting these pathways, specifically by inhibiting TNF-α and IL-6, can reduce tumour growth and improve clinical outcomes in preclinical models of HCC." (PMID 40544399, 2025). "As a result, these TAK1 mutants defected TAK1's oncogenic functions to promote cancer cell proliferation, tumor growth in vivo, and elevate p65 downstream targeted genes such as TNFα, IL‐6 and IL‐1β.." (PMID 40999870, 2025). "High-risk genes (TNF, CXCL1, CCL20, ITGA5, CXCL3) typically promote tumor progression and immune evasion by inducing the expression of chemokines or modulating cellular responses to chemokines." (PMID 40517358, 2025). "High STAT3 expression was positively associated with epithelial apoptotic processes, suggesting enhanced tumor suppression through regulated cell death, and with TNF-α signaling via NFκB, indicating robust anti-tumor immunity." (PMID 40636126, 2025). "Activated NK cells produce cytotoxic molecules, including perforin and granzyme that can eliminate tumor cells and activate apoptotic pathways in tumor cells by producing TNFα." (PMID 40437549, 2025). "The findings also revealed that TNF-α directly promotes the survival of tumor cells in vivo by limiting apoptosis, contributing to the formation of MPE." (PMID 39759851, 2025). "At the same time, TNF-α regulates macrophage polarization toward the M2 phenotype and promotes tumor progression and metastasis by activating complex cytokine networks." (PMID 40109347, 2025). "CRISPR screens have revealed the importance of TNF-α signal transduction mediators, such as TAK1, in facilitating tumor susceptibility to cytotoxic T cells." (PMID 41102176, 2025). "Proinflammatory cytokines, such as tumor necrosis factor (TNF), IL-6, and IL-1β, typically drive tumor progression by enhancing tumor cell proliferation, survival, and invasive potential, as well as promoting angiogenesis." (PMID 40563367, 2025). "After intradermal administration, the micelles promoted secretion of pro‐inflammatory cytokines (i.e., IFN‐γ, TNF‐α, IL‐4, IL‐6, IL‐12) and increased tumor infiltration of CD4+ and CD8+ T cells for robust antitumor immune responses." (PMID 41287898, 2025). "Hepatocellular carcinoma studies further demonstrate differential PRG expression across immune cells, such as upregulated CRADD in tumor-infiltrating Tregs versus elevated TNF in cytotoxic FGFBP2+ T cells." (PMID 40721869, 2025). "In this formulation, TNF-α disrupted tumor vasculature, facilitating paclitaxel penetration into the tumor tissue for a synergistic antitumor effect." (PMID 41049749, 2025). "The regulatory role of CD8 + T cells in OC TME is crucial as these cells can remove tumor cells by secreting granzyme B, TNF and IFN-γ." (PMID 40369674, 2025). "Macrophages and neutrophils in the tumor microenvironment shape a cytokine milieu (IL-6, IL-1β, TNF, CXCL8) that supports tumor growth and metastasis and counteracts antitumor immunity." (PMID 41440484, 2025).
tumor (continued). "Preclinical models consistently demonstrate post-HIFU up-regulation of pro-inflammatory cytokines (e.g., IFN-γ, TNF-α) and recruitment of tumor-specific cytotoxic T lymphocytes, culminating in systemic anti-tumor immunity." (PMID 41228308, 2025). "Antigen pulsing was performed by culturing the mDCs in the presence of cytokines rh-IL-4, rh-GMC-SF, rh-IL-6, rh-IL1b, rh-IL12, rh-IL-15, and rh-TNF-α and incubating 106 cells with 18 μg of tumor lysate or cultured cell lysate for 18 h." (PMID 40733726, 2025). "The resulting defect in LFA-1 activation was associated with CD8+ T cell hyporesponsiveness, evidenced by diminished production of key anti-tumor mediators such as TNF-α and IFN-γ." (PMID 39911389, 2025). "Most of the genes are enriched in the TNF, NF-kappa B, and IL-17 signaling pathways, all of which are closely related to tumor apoptosis and proliferation." (PMID 41155419, 2025). "As a pleiotropic cytokine, TNF-α plays a dual role in cancer biology—capable of initiating both antitumor immunity and tumor-promoting inflammation depending on the cellular context." (PMID 41401147, 2025). "This is primarily because M1 macrophages can secrete various pro-inflammatory factors (e.g., TNF-α, IL-12) and generate ROS, which directly or indirectly kill tumor cells while activating the host immune system, thereby inhibiting tumor growth and metastasis." (PMID 41394807, 2025). "M1-type TAMs exhibit anti-tumor properties and are capable of releasing pro-inflammatory cytokines such as TNF-α and IL-12, which serve to activate immune cells to target and eliminate tumor cells." (PMID 41394878, 2025). "Therapeutic strategies based on TNF-α need to enhance its anti-tumor ability while at the same time avoiding its tumor-promoting effects." (PMID 41376630, 2025). "M1 macrophages limit tumor growth by secreting proinflammatory cytokines such as IL-6, IL-8, and TNF-α." (PMID 40070576, 2025). "Normally, M1 macrophages have anti-tumor properties, producing nitric oxide (NO) and TNFα, which promote cancer cell death." (PMID 40330466, 2025). "Mishalian and colleagues have shown that neutrophils from early tumors display potent cytotoxic effects on tumor cells through increased production of TNF-α, NO, and H2O2." (PMID 41254689, 2025). "Taken together, our results demonstrate that signaling of TNF-α and IL-1 is crucial for the antitumor effect mediated by Cad-KO tumor cells." (PMID 41243973, 2025). "Our data indicated that treatment with quadrigemine I significantly reduced the secretion of key pro-inflammatory cytokines, such as TNF-α, IL-6, and IL-1β, in various tissues, including serum, liver, spleen, and tumor tissues." (PMID 40429988, 2025). "For example, in the S180 solid tumor mouse model, a 100 mg/kg dose of Codonopsis glucosamine inhibited tumor growth more significantly than a 50 mg/kg dose, and was able to significantly elevate the expression of TNF-α." (PMID 40351428, 2025). "In BCBM, CCL2 can be spontaneously generated by BC cells through NF‐κB, TNFα, and other pathways and can also be generated by tumor cells stimulated by microenvironment, or by stromal cells." (PMID 39712454, 2025). "The activation of this pathway is associated not only with the proliferation of endothelial cells in the tumor microenvironment but also with the maintenance of tumor cell survival by inhibiting TNF-α-dependent apoptosis, further promoting vascular formation." (PMID 40438141, 2025). "This inflammatory state promotes the release of cytokines (e.g., IL-1β, IL-6, IL-10, IL-18, TNF-α) and growth factors that facilitate tumor cell proliferation, invasion, and angiogenesis, while simultaneously impairing immune surveillance." (PMID 41114747, 2025). "Studies have shown that TNF-α can promote tumor proliferation, migration, invasion, and angiogenesis." (PMID 40699763, 2025).